RNU6-487P (RNA, U6 small nuclear 487, pseudogene)
Gene: Small nuclear RNA gene on chromosome 1 (203,318,996 to 203,319,099, reverse strand). Ensembl gene ENSG00000202300.
Homologues: Orthologues: chimpanzee U6 (99% identical), macaque U6 (97% identical), guinea pig U6 (93% identical), guinea pig U6 (91% identical). Paralogues in human: RNU6-1 (93% identical), RNU6-15P (93% identical), RNU6-2 (93% identical), RNU6-3P (93% identical), RNU6-4P (93% identical), RNU6-5P (93% identical), RNU6-6P (93% identical), RNU6-9 (93% identical), RNU6-10P (92% identical), RNU6-12P (92% identical), RNU6-13P (92% identical), RNU6-14P (92% identical), and 1285 more.